INS (insulin)
Diseases named in the same sentence as INS in open-access papers (continued):
Sharing a sentence is not in itself a finding about the gene and the disease.
Insulin resistance (continued). "Inositol plays a key role in insulin transduction signaling, and the deregulation of inositol metabolism has been demonstrated in different conditions of insulin resistance, which has been associated with several cancers." (PMID 39199391, 2024). "Xanthurenic acid is another metabolite in the KYN-nicotinamide adenine dinucleotide pathway that creates an antigenic compound unrecognizable from insulin by reacting with insulin and eventually causes insulin resistance by reducing insulin sensitivity." (PMID 38321994, 2024). "While insulin resistance in the hypothalamus seems to hinder the acute stimulation of pancreatic insulin release, it was found to be paradoxically associated with insulin hypersecretion in response to oral glucose load in a cross-sectional study." (PMID 38363340, 2024). "Accordingly, studies in Japanese subjects who exhibit milder abdominal obesity showed that impaired insulin clearance causes hepatic insulin resistance and steatosis." (PMID 39640841, 2024). "Reduced insulin sensitivity (insulin resistance) is a hallmark of normal physiology in late pregnancy and also underlies gestational diabetes mellitus (GDM)." (PMID 38627562, 2024). "In light of the limitations above, the primary objective of this study was to investigate the potential association between non-insulin-based insulin resistance indices and the development of DN among diabetic patients in the context of the U.S. population." (PMID 39720248, 2024). "Insulin resistance plays an important role in the causation of AD and other neuropsychiatric diseases through pathways like impaired insulin signaling, inflammation, and disrupted glucose metabolism." (PMID 39518747, 2024). "The liver is susceptible and experiences insulin impairment more rapidly than other organs; consequently, hepatic insulin resistance is the initial event that paves the way for peripheral tissue insulin resistance." (PMID 39768643, 2024). "Elevated blood irisin levels were found to be positively associated with insulin resistance, and reduced insulin clearance was observed in adult individuals in association with higher circulating irisin levels." (PMID 39769243, 2024). "The low-grade inflammation associated with obesity can impair insulin signaling, causing insulin resistance, and subsequent metabolic problems." (PMID 39519540, 2024). "Previous studies have shown that proinflammatory factors can cause insulin resistance by interfering with insulin signaling pathways, such as IKKβ/NF-κB pathway, JNK pathway and inflammasome pathway, and thus increase GLU0min." (PMID 39655348, 2024). "When consumed in excessive amounts, it can lead to insulin resistance, a condition in which the body’s cells become less responsive to insulin, leading to high blood sugar levels and an increased risk of developing type 2 diabetes." (PMID 38667785, 2024). "Even in individuals of normal weight, an excess of EAT can elevate the risk of insulin resistance (IR) and impair insulin secretion." (PMID 39911240, 2024). "Glut-4 expression in insulin-sensitive tissues decreases in association with whole-body insulin resistance and high levels of inflammatory markers in a rat model of metabolic syndrome." (PMID 38396865, 2024). "Folic acid indirectly increases insulin sensitivity by lowering levels of homocysteine, an amino acid associated with insulin resistance." (PMID 39683416, 2024). "Some studies indicate that several diseases related to metabolic syndrome (MetS) are associated with low MQI/BMI and increased mortality due to insulin resistance, which has an inverse correlation with insulin sensitivity." (PMID 38397883, 2024). "The severity of AN in children is associated with higher fasting insulin levels and Homeostatic Model Assessment for Insulin Resistance (HOMA-IR) score, indicative of insulin resistance." (PMID 39432507, 2024).
Insulin resistance (continued). "Fatty acid accumulation causes insulin resistance through insulin signaling cascades, which counteracts increased glucose uptake and glycolysis." (PMID 38834564, 2024). "It has been reported that hyperactive BECN1 can activate autophagy in response to cellular stress caused by insulin resistance, helping to alleviate the pathology, enhance systemic insulin sensitivity, and regulate energy metabolism." (PMID 39610878, 2024). "SHBG was also associated with higher insulin sensitivity and β-cell function and inversely associated with insulin resistance ∼3 years later." (PMID 39055720, 2024). "Abnormalities within the insulin signaling pathway represent both the cause and consequence of insulin resistance." (PMID 39749015, 2024). "For instance, insulin deficiency is present at disease onset in T1DM, whereas insulin is elevated in the early phase of T2DM as a result of insulin resistance." (PMID 39037711, 2024). "Systemic inflammation during severe infections, as well as exposure to pro-inflammatory cytokines like TNF and IFNγ, is closely associated with a reduction in insulin’s intracellular effects, a condition referred to as insulin resistance." (PMID 39768214, 2024). "Reducing the risk of type 2 diabetes: vitamin D3 can improve insulin sensitivity, thus reducing the risk of insulin resistance and type 2 diabetes development, which are components of metabolic syndrome." (PMID 38732523, 2024). "Insulin resistance (IR) is a metabolic disorder associated with obesity, where the sensitivity and cellular response to insulin in tissues is decreased, as well as glucose metabolism." (PMID 39123622, 2024). "Hepatic insulin resistance causes the failure of insulin-mediated secretion of very low-density lipoprotein (VLDL)." (PMID 39598339, 2024). "In another study, authors showed that 12 weeks of KD (79.1% fat and 3.8% carbohydrate) induce insulin resistance associated with impaired hepatic insulin signaling." (PMID 38577162, 2024). "Elevated FFAs interfere with insulin signaling pathways, causing insulin resistance in peripheral tissues such as muscle and liver." (PMID 39104999, 2024). "Chronic inflammation, implicated in insulin resistance and type 2 diabetes pathogenesis, is mitigated by VD within the pancreas, thereby preserving beta cell function and insulin secretion." (PMID 38910623, 2024). "Elevated circulating insulin levels are a hallmark of insulin resistance, which is closely linked to increased oxidative stress and inflammation." (PMID 39594500, 2024). "Hyperinsulinemia can cause insulin resistance in lean individuals and induce obesity through the action of insulin on lipogenesis." (PMID 39049964, 2024). "This condition is associated with insulin resistance, where cells become less responsive to insulin's effects." (PMID 38481895, 2024). "Drugs from the PI group inhibit the action of GLUT-4 in peripheral tissues, causing impaired insulin secretion and contributing to the development of insulin resistance." (PMID 39124846, 2024). "T2DM, one of the greatest threats to global public health in the western world, is associated with obesity, insulin resistance, and, eventually, with reduced insulin secretion." (PMID 38550379, 2024). "Insulin resistance, characterised by a deficiency in insulin-mediated glucose transport into muscle and fat tissues, is one of the earliest indicators of cardiometabolic disorders." (PMID 38960128, 2024). "Asprosin also impairs insulin signaling and causes inflammation, endoplasmic reticulum stress, and insulin resistance." (PMID 38438865, 2024). "The chief pathophysiologic factors that cause T2DM are peripheral insulin resistance and the last devastation of insulin creator pancreatic cells." (PMID 39725830, 2024). "Visceral fat accumulation can interfere with endocrine metabolism because lipid metabolites are lipotoxic, hinder insulin signal transduction, and cause insulin resistance." (PMID 39027477, 2024).
Insulin resistance (continued). "Inflammation disrupts insulin signaling cascades by activating kinase molecules, causing insulin resistance." (PMID 39335530, 2024). "Low levels of adiponectin have been associated with obesity, oxidative stress, and insulin resistance, whereas higher levels are associated with improved insulin sensitivity in adipose tissue." (PMID 38201996, 2024). "Fasting insulin-increasing alleles (35 variants also associated with higher fasting glucose, indicative of insulin resistance) were associated with lower relative childhood adiposity (P = 3.8 × 10−3) and lower adult BMI (P = 1.4 × 10−5)." (PMID 39174749, 2024). "In 1-day larvae, several DEGs were associated with insulin signaling pathways and insulin resistance, suggesting that glucose and lipid metabolisms were involved in the process of N. bombycis infection." (PMID 38556880, 2024). "The mechanism by which NAFLD is associated with hepatic insulin resistance is believed to be due to increased hepatic diacylglycerol, which activates protein kinase C, resulting in decreased insulin signaling." (PMID 39408924, 2024). "High insulin resistance or low insulin secretion boosts lipase activity, on the other hand, causing excess free fatty acids that the liver cannot oxidize, leading to NAFLD11." (PMID 38576946, 2024). "The development of insulin resistance has also been linked to the direct effects of the virus on the pathway insulin signaling." (PMID 39457712, 2024). "High insulin levels associated with euglycemia suggests insulin resistance as reported by the calculated HOMA-IR." (PMID 38553002, 2024). "The disability of cells to react to insulin, causing glucose intolerance and hyperglycemia, is referred to as insulin resistance." (PMID 38425702, 2024). "Insulin resistance (IR) characterizes reduced sensitivity and responsiveness to insulin in muscle, liver and β cells, and is linked to impaired glucose tolerance as pre-diabetes." (PMID 38566188, 2024). "Recent genetic analyses on the causal effects of insulin resistance on the systemic metabolism also give explicit support on the key role of insulin in explaining the metabolic findings." (PMID 38191968, 2024). "Observational studies have consistently shown an association between VD deficiency, impaired insulin secretion, insulin resistance, and heightened risk of type 2 diabetes." (PMID 38910623, 2024). "Studies have shown that in the prediabetes stage, the risk of CVD increases owing to the presence of strong insulin resistance and low endogenous insulin secretion in the body, which in turn leads to the development of atherosclerotic vascular lesions." (PMID 38302943, 2024). "Increased INS levels are associated with nutritional and insulin resistance in late pregnancy and early lactation." (PMID 39748870, 2024). "After menopause, women gradually develop obesity and insulin resistance and are at high risk of type 2 diabetes, but hormone replacement therapy improves insulin sensitivity and glycemic control." (PMID 38649684, 2024). "Specifically, PTP1B-deficient rats exhibit decreased TNF-α-dependent insulin resistance and increased insulin sensitivity in adipose tissue and skeletal muscles." (PMID 38431555, 2024). "HepG2 IGF1R KO cells exposed to long-term pathological insulin concentrations exhibited the hallmark characteristics of insulin resistance, such as decreased levels of AKT phosphorylation upon 5-minute insulin stimulation." (PMID 39572596, 2024). "As for the cause of glucose intolerance in patients with pheochromocytoma, α2 receptors are mainly involved in decreased insulin secretion, while α1, β2, and β3 receptors in each tissue are associated with insulin resistance." (PMID 39384339, 2024). "T2DM is caused by chronic decreasing tissue insulin sensitivity, known as insulin resistance, combined with reduced synthesis of insulin due to the loss of insulin-producing pancreatic beta cells resulting in hyperglycemia." (PMID 38384596, 2024).
Insulin resistance (continued). "Elevated levels of pro-inflammatory cytokines such as Interleukin-6 (IL-6) and tumor necrosis factor-alpha (TNF-α) are implicated in insulin resistance by disrupting the insulin signaling pathway." (PMID 39691364, 2024). "Studies have suggested 12-OH/non-12-OH BAs ratio as a potential biomarker for hyperglycemia and insulin resistance, since a higher ratio is associated with islet signaling, higher blood glucose, and lower insulin sensitivity." (PMID 39355267, 2024). "Lower hepcidin levels are linked to insulin resistance, and insulin sensitivity is improved by reducing the iron load via blood donations, indicating a causal relationship." (PMID 40895225, 2024). "Activated JNK inhibits insulin signaling via serine phosphorylation of the substrate proteins of insulin receptor, leading to the development of insulin resistance and consequently an increased risk of elevated glucose." (PMID 39590972, 2024). "It is caused by insulin resistance in insulin-sensitive tissues and impaired insulin secretion of pancreatic β-cell." (PMID 38704482, 2024). "Excess fat, particularly visceral fat, is known to adversely affect the hormonal and metabolic systems, increasing insulin levels and insulin resistance, which are associated with poorer outcomes in the diagnosis and treatment of breast cancer." (PMID 39791640, 2024). "Central to this association of AD-obesity-T2D is insulin resistance, a key factor leading to decreased insulin sensitivity, hyperglycemia, and impaired glucose uptake." (PMID 39595866, 2024). "Impaired insulin sensitivity will lead to insulin resistance, which is associated with metabolic syndromes (MetS) such as hypertension and dyslipidemia." (PMID 38337642, 2024). "T2DM is a metabolic disorder characterised by chronic hyperglycaemia, which is a direct consequence of insulin resistance (IR), defined as a blunted response of tissues to the pancreatic hormone insulin and recognised as the hallmark of T2DM." (PMID 39408212, 2024). "They created a GRS for beta cell dysfunction and insulin resistance based on 35 SNPs associated with insulin secretion and 20 SNPs associated with insulin sensitivity, respectively, in Asian populations." (PMID 38039081, 2024). "A long-term KD results in glucose intolerance associated with inadequate insulin secretion, insulin resistance, and reduced beta and alpha cell mass in mice." (PMID 38892561, 2024). "VFA and PBF are linked to insulin resistance and steatotic liver disease via reduced hepatic clearance of insulin (exacerbating hyperinsulinemia), increased production of triglyceride-rich lipoproteins, and elevated hepatic glucose production." (PMID 38883602, 2024). "Obesity-mediated low-grade inflammation, the expression of adipose tissue-specific cytokines, and inflammatory cytokines secreted by visceral adipocyte are some of the causes of systemic insulin resistance leading to low insulin sensitivity." (PMID 39056667, 2024). "This information is essential for understanding the long-term impacts of diets on insulin production and the risk of developing insulin resistance or type 2 diabetes." (PMID 39126081, 2024). "The mechanisms leading to hyperglycemia are believed to be caused by impaired insulin secretion and insulin resistance." (PMID 39410536, 2024). "The degree of insulin resistance was associated with biomarkers, such as adiponectin, tumor necrosis factor-α, branched-chain amino acids, the visceral fat area, and the dose of insulin required for glycemic control." (PMID 38905235, 2024). "In conclusion, both metabolic syndrome and insulin resistance are linked to obesity-associated colon cancer through changes in insulin, and the IGF system." (PMID 39201522, 2024). "This is because in addition to increased circulating levels of these metabolites, elevated levels of inflammatory cytokines, which in themselves can alter insulin signaling and cause insulin resistance, are a feature of obesity/insulin resistance." (PMID 39163364, 2024).
Insulin resistance (continued). "The increase in these cytokines causes adipocyte dysfunction and inhibits insulin signaling, leading to insulin resistance." (PMID 38543073, 2024). "Increased PPAR-γ expression is associated with improved insulin sensitivity and reduced insulin resistance." (PMID 39771098, 2024). "IL (interleukin)-6 has been linked to insulin resistance, particularly in obesity-related metabolic disorders, interfering with insulin signaling and contributing to systemic inflammation." (PMID 38893645, 2024). "Some studies proved that the presence of FOXP3+ Tregs was associated with improved insulin sensitivity, while their depletion in the visceral fat of obese mice was correlated with insulin resistance." (PMID 39518420, 2024). "One possible explanation is that the MD, rich in whole grains, fruits, and vegetables, can improve insulin sensitivity and regulate blood sugar levels, reducing the risk of insulin resistance, which is often linked to liver disease." (PMID 39458545, 2024). "DC12 can overcome such metabolic derangement, preserving the pancreatic insulin secretion machinery and avoiding insulin resistance associated glucose intolerance." (PMID 38959440, 2024). "Hyperinsulinemia, caused by insulin resistance, when the amount of insulin in the blood is higher than what is considered normal, is often associated with T2DM." (PMID 37880477, 2024). "Leptin levels are positively associated with insulin resistance while adiponectin has potent insulin-sensitizing effects and enhances insulin secretion." (PMID 38256626, 2024). "This dyslipidemia can lead to an accumulation of fatty acids in tissues such as muscle and liver, which can interfere with insulin signaling and exacerbate insulin resistance, thereby increasing the risk of GDM." (PMID 38414896, 2024). "In T2DM, the main factors underlying the development of MASLD are insulin resistance, impaired insulin secretion and abnormalities in glucose and lipid metabolism." (PMID 39376658, 2024). "On the other hand, because a key underlying mechanism of type 2 diabetes was insulin resistance driven in part by chronic hyperglycemia, as carbohydrate consumption increases, insulin resistance increases in a linear manner." (PMID 38721664, 2024). "Pearson’s correlation helped us to explore the association between several insulin resistance indexes, including fasting glucose, fasting insulin, and HOMA-IR, as well as anthropometric markers, including the WHtR, WC, and WHR." (PMID 39717101, 2024). "Muscle strength showed an inverse association with insulin levels, insulin resistance, and type 2 diabetes, and sarcopenia demonstrated a significant association with insulin resistance, particularly in the elderly." (PMID 38612998, 2024). "FFA can cause insulin resistance in all major insulin target organs (skeletal muscle, liver, endothelial cells) and has become a major link between obesity, T2DM, and atherosclerotic vascular diseases." (PMID 39713052, 2024). "Insulin resistance is primarily caused by the inability of insulin to effectively activate the insulin receptor substrate (IRS)." (PMID 39518747, 2024). "TRPA1, a channel that has been extensively studied for its association with glucagon-like peptide-1 (GLP-1) and insulin secretion, is suitable as an effective therapeutic target for dietary insulin resistance and associated diseases." (PMID 39273183, 2024). "Insulin resistance, a condition commonly associated with obesity, occurs when cells become less responsive to the effects of insulin." (PMID 39411599, 2024). "While in type-2 DM insulin production by β cells is unaffected but patients of this type suffer from insulin deficiency and insulin resistance that the cells of the body can't utilize insulin to regulate BGL." (PMID 38186949, 2024). "CME and FCME decrease plasma insulin levels, insulin resistance, and plasma biomarkers associated with obesity and lipid accumulation." (PMID 39598313, 2024).